CLDN18 (claudin 18)
Diseases named in the same sentence as CLDN18 in open-access papers (continued):
Sharing a sentence is not in itself a finding about the gene and the disease.
tumor (continued). "GS tumours show RAS homologue gene family, member A (RHOA) and E-cadherin (CDH1) gene mutations and the Claudin-18 (CDLN18)-Rho GTPase activating protein 6/26 (ARHGAP6/26) translocation." (PMID 31235864, 2019). "A tumour was considered as CLDN18 heterogeneous in case of concomitant presence of high-CLDN18 and low-CLDN18 TMA cores." (PMID 31235864, 2019). "Intratumoural variability of membranous CLDN18 expression was investigated, considering CLDN18 expression among the multiple TMA cores collected from different areas of the same tumour." (PMID 31235864, 2019). "In 108/510 (21.2%) primary tumours, only a weak (i.e. 1+) CLDN18 expression was observed, and only 26 (5.1%) of these cases were classified as high CLDN18 tumours." (PMID 31235864, 2019). "In 47/95 (49.5%) cases with nuclear staining, a concurrent membranous positivity was observed and only 10 of them were categorised as high CLDN18 tumours." (PMID 31235864, 2019). "The trend was more pronounced for the GC group, in which PD-L1-positive cases showed a higher prevalence of EBER-positive cases (7.3%), MMRd tumours (34.1%) and CLDN18 high expression (41.5%)." (PMID 31235864, 2019). "PD-L1-positive cases showed a trend towards a higher prevalence of EBER positivity (6.7% vs 3.0%), MMRd tumours (31.1% vs 22.4%) and CLDN18 high expression (38.8% vs 29.7%)." (PMID 31235864, 2019). "A 38.8% of the cases showed significant CLDN18 intratumoural variability among the different tissue microarray cores obtained from the same tumour." (PMID 31235864, 2019). "Cohort 4 will evaluate the combination of first-line zolbetuximab, mFOLFOX6, and nivolumab in intermediate-to-high CLDN18.2 positivity (2+/3+ IHC in ≥75% of tumor cells [high] or ≥50% but <75% of tumor cells [intermediate]), HER2-negative metastatic GAC/GEJ patients." (PMID 40136475, 2025). "First, future research should focus on identifying patient subgroups that may benefit cost-effectively from switch maintenance therapy through the exploration of additional tumor biomarkers such as CLDN18.2 or mismatch repair status." (PMID 41020007, 2025). "Therefore, a subsequent phase-III trial was initiated in China to further explore these results in patients with CLDN18.2 positive, which is defined as ≥40% of tumor cells, advanced GET (NCT06206733)." (PMID 39941712, 2025). "The adoption of standardized testing across tumor types, accounting for intratumoral heterogeneity and primary–metastatic discordance, will be essential to identify potential patients eligible for clinical trials targeting CLDN18.2." (PMID 41374966, 2025). "Specifically, regarding immunohistochemistry, inclusion criteria were HER2-negative and CLDN18.2-positive tumors, where the threshold for considering a case as positive for CLDN18.2 was set at 75% of tumor cells demonstrating moderate to high membranous staining." (PMID 40835751, 2025). "17/64 tumors were CLDN18.2-positive in the whole-tumor section cohort (26.6%)." (PMID 40775258, 2025). "Cohort C is evaluating osemitamab plus CAPOX as first-line therapy for CLDN18.2-positive (IHC ≥ 1+ in ≥10% of tumor cells), HER2-negative or unknown, advanced/metastatic GAC/GEJ." (PMID 40136475, 2025). "The utility of CLDN18 for image-guided surgery has been described and two CLDN18-specific imaging probes were able to facilitate the resection of tumor tissue in orthotopic mouse tumor models." (PMID 40379788, 2025). "However, during malignancy, tight junction proteins can become disrupted, exposing Claudin-18 epitopes on tumor cells." (PMID 39813112, 2025). "The Claudin-18 protein is a tetraspanin that is encoded by the multigene CLDN family and is a key component of tight junctions; it plays roles in the proliferation, differentiation, and migration of tumor cells." (PMID 39813112, 2025). "Notably, patients with medium-to-high CLDN18.2 expression (≥2+ membranous staining in ≥40% of tumor cells) and known combined positive score (CPS) demonstrated enhanced clinical benefit." (PMID 41374966, 2025).
tumor (continued). "Notably, in a subgroup of 32 GC patients with moderate-to-high (IHC 2+/3+) CLDN18.2 expression in ≥25% of tumor cells, the ORR and DCR rose to 71.9% (95% CI: 53.3–86.3%) and 96.9% (95% CI: 83.3–99.9%), respectively." (PMID 41374966, 2025). "One study found that CLDN18 knockout mice were more likely to develop intraepithelial neoplasm and polypoid tumors, suggesting that it may play a tumor-suppressive role." (PMID 41374966, 2025). "Phase I/II clinical trials of tecotabart vedotin plus immune checkpoint inhibitor toripalimab (NCT05188664 and NCT05934331) revealed ORR of 73% (24/33) in G/GEJAC or esophageal adenocarcinoma patients with CLDN18.2 staining of 2+/3+ intensity in at least 25% of tumor cells." (PMID 41164107, 2025). "There was a clear trend between CLDN18.2 expression and anti-tumor efficacy for this cohort." (PMID 40136475, 2025). "By restricting activation of 4-1BB to cells with CLDN18.2 positivity, the hope was to achieve targeted anti-tumor activity with a decreased potential for hepatotoxicity, which had previously occurred in patients treated with urelumab and utomilumab, 4-1BB agnostic mAbs." (PMID 40136475, 2025). "We could answer the questions: (a) are endoscopic biopsies able to provide a realistic picture of the actual CLDN18.2 status of the whole tumor and (b) if the first question can be answered with “yes”, how many tumor-bearing biopsies are necessary?" (PMID 40775258, 2025). "A phase III randomized clinical trial of arcotatug tavatecan monotherapy versus the investigator’s choice of therapy (G-HOPE-001 study, NCT06238843) is recruiting G/GEJAC patients with CLDN18.2 membrane staining of 2+/3+ intensity in at least 75% of tumor cells." (PMID 41164107, 2025). "Fewer tumor-bearing biopsies worsened the correct detection rate of CLDN18.2 positive tumors." (PMID 40775258, 2025). "This is the first analysis of the concordance of CLDN18.2 positivity in archival versus baseline tumor samples; although concordance was high in this study, future research may further clarify the reasons for nonconcordance observed in some patient tumors." (PMID 38954176, 2024). "In our study, we identified an HLA-A*11:01-binding immunogenic neoantigen peptide P1 (RTEDEVYNSNK) derived from CLDN18-ARHGAP gene fusion and successfully induced NRT cells with strong tumor-killing ability in both cell lines and mouse models with CLDN18-ARHGAP gene fusion." (PMID 39164472, 2024). "Additionally, CLDN6 and CLDN18 have been proposed as targets for tumor inhibition in proof-of-concept studies." (PMID 38540693, 2024). "We also report the concordance of CLDN18.2 positivity in a subset of pair-matched samples consisting of archival tumor samples and baseline tumor samples from the phase 2 ILUSTRO study (NCT03505320; cohorts 1A and 2) and a phase 1 study in Japanese patients (NCT03528629)." (PMID 38954176, 2024). "Moreover, the presence of the CLDN18 fusion was also confirmed by us through fluorescence in situ hybridization (FISH) in tumor tissues of PC GC patients." (PMID 39164472, 2024). "In addition, we showed intratumoral CLDN18 heterogeneity with a tendency to decrease from the superficial to the deep side of the primary tumor, which is in line with earlier publications." (PMID 38724721, 2024). "However, a recently presented study reported the prevalence and biomarker analysis of over 4000 locally advanced unresectable or metastatic GC tumor samples tested for CLDN18.2 status from two different studies." (PMID 38339430, 2024). "Furthermore, IL-6, CXCR4, CXCL8, and MMP-9 indicate higher diagnostic utility based on the area under the ROC curve (AUC) than well-established OC tumor markers, whereas CLDN18.2 can be used in novel targeted therapies for OC patients." (PMID 38673838, 2024).
tumor (continued). "The NetMHCpan 4.0 was used to predict potential peptides derived from three CLDN18-ARHGAP fusion types previously reported to be present in tumor samples, including junctions of CLDN18 (exon 5)-ARHGAP26 (exon 12), CLDN18 (exon 5)-ARHGAP26 (exon 10) and CLDN18 (exon 5)-ARHGAP6 (exon 2)." (PMID 39164472, 2024). "The enhanced tumor accumulation of Nano/CLDN18.2 and NanoBE could be attributed to the modification with anti-CLDN18.2 scFv, which facilitated binding to CLDN18.2 on the tumor cells." (PMID 38468289, 2024). "Additionally, CLDN18 staining intensity and the fraction of stained tumor cells were significantly correlated, consistent with previous findings." (PMID 37629433, 2023). "In addition, CLDN18 was significantly associated with markers of activated CD8 + T cells and CD4 + T cells after adjusting for tumor purity." (PMID 37438735, 2023). "This phase III trial randomised 575 patients to either zolbetuximab or placebo using mFOLFOX6 (5-FU, leucovorin and oxaliplatin combination chemotherapy) as the chemotherapy backbone and included patients with moderate-to-strong CLDN18 staining in ≥75% of tumour cells on IHC." (PMID 37370858, 2023). "Furthermore, CLDN18 was significantly overexpressed in HCC tumor tissues compared to the adjacent non-tumor tissues, which was consistent with PBMC sequencing results and also validated with the immunohistochemical data from human protein profiles." (PMID 37438735, 2023). "In addition, much lower level of mRNA expressions of CXCL12 which mainly produced by CAFs in the tumor site was observed in the FAP-mBBZ CAR-T group than those from CLDN18.2-mBBZ CAR-T and UTD groups." (PMID 37046312, 2023). "Together, these studies support the consideration of biomarker testing for tumor expression of CLDN18.2 and the use of zolbetuximab as a first-line therapy in combination with chemotherapy as a new potential standard of care in this biomarker-selected patient population." (PMID 37524953, 2023). "Patients had to have at least 50% CLDN18.2 expression of tumor cells." (PMID 36873983, 2023). "In addition, a study of Japanese patients with gastric adenocarcinoma revealed that moderate-to-strong CLDN18.2 expression positively correlated with a higher grade of dedifferentiation (59.0% vs. 37.7% for G3 and G1/2 tumours, respectively; P = 0.005)." (PMID 36969060, 2023). "Additionally, the sequential treatment led to increased CAR copies in tumor tissues than twice treatment of CLDN18.2-mBBZ CAR-T cells (p < 0.05)." (PMID 37046312, 2023). "Thus, FAP-targeted CAR-T cells are likely to attack CLDN18.2-positive tumor cells at the initial stage of treatment in our animal experiment by this mechanism." (PMID 37046312, 2023). "Furthermore, in the subpopulation with very high CLDN18.2 expression (≥ 2+ intensity in ≥70% tumor cells), efficacy was more pronounced (mOS 9 vs. 16.7 mo; HR 0.45; p < .001)." (PMID 35642043, 2022). "On the contrary, CLDN18 was expressed by normal gastric cells and downregulated in tumor cells." (PMID 35999201, 2022). "CLDN18 was also proposed to be a tumor suppressor gene for LUAD." (PMID 36067196, 2022). "However, high expression levels of CLDN18 (2+ and 3+ intensity in ≥75% tumor cells) were found in 117/350 (33.4%) patients (98 primary cases, 19 metastases) and 158/350 (45.1%) patients presented at least 50% of the cancer cells stained for CLDN18." (PMID 34834447, 2021). "Moreover, preplanned analyses from the FAST trial showed that higher levels of expression of CLDN18 (≥2+ in ≥70% of tumor cells) achieved a greater treatment advantage of zolbetuximab than lower levels." (PMID 34834447, 2021). "This suggests a role of Claudin 18 in ensuring EBV maintenance in tumor cells." (PMID 32668412, 2020). "In fact, 14/20 (70%) of EBER-positive tumours showed high expression of CLDN18." (PMID 31235864, 2019). "Higher prevalence of positive E-cadherin was found among positive CLDN18 tumours." (PMID 31235864, 2019).
tumor (continued). "Our immunohistochemical analysis showed that almost all CLDN18-ARHGAP26 fusion-positive cases expressed CLDN18, about half of which expressed ARHGAP26 in the membrane, which likely reflects the requirement of CLDN18 promoter activity for expression of the fusion protein in tumor cells." (PMID 30034621, 2018). "A recent study highlighted different rates of CLDN18 positivity in FNBs vs. surgical specimens; this striking finding leads the consensus panel to its strong recommendation that at least 50 viable infiltrating tumor cells should be evaluated in order to obtain a reliable result." (PMID 40835751, 2025). "Furthermore, the overexpression of CLDN18 could enhance the barrier function of tumor cells, obstructing macrophage contact with and recognition of tumor cells." (PMID 38774870, 2024). "In addition, differences in CLDN18 expression between tumor samples and normal samples were present in only certain cancers, indicating that the development of other cancers may not lead to significant differences in CLDN18 expression." (PMID 39555091, 2024). "Moreover, the presence of fusion proteins may disrupt the structure of wild-type CLDN18 protein, subsequently impacting cancer-cell adhesion and promoting tumor migration and invasion." (PMID 38717722, 2024). "To determine whether the positivity of CLDN18 depends on the number of tissue fragments obtained by biopsy, we examined the relationship between the number of fragments containing tumor tissue and CLDN18 positivity in 78 cases for which biopsy samples were available." (PMID 38724721, 2024). "Treatment with anti-CLDN18.2-anti-CD28 also produced more interferon-γ (IFN-γ) and tumour necrosis factor-α (TNF-α) in splenocytes and reduced the levels of immunosuppressive cells, including tumour-associated macrophages and myeloid-derived suppressor cells, in tumour tissues." (PMID 36969060, 2023). "Positive CLDN18 expression was associated with lower node stage (N0 vs. N1–2), with a higher prevalence of positive expression among the N0 stage (p = 0.045), but not with the tumor stage." (PMID 37629433, 2023). "In addition, CLDN18 was also associated with tumor infiltrating immune cells, suppressive immune cell markers, T lymphocyte depletion and activation of HCC, and low expression of CLDN18 was associated with higher CD8 + T cell infiltration and better survival rates." (PMID 37438735, 2023). "Thus, approximately 30% of patients with CLDN18.2-positive tumor could be excluded from the treatment." (PMID 36922936, 2022). "Beyond these three claudins, claudin-18 is often lost in tumours, inducing gastric cancer, subsequently affecting cytokines and stemness; additionally, it might also relate to Wnt-signaling pathways in other tumour types." (PMID 36291586, 2022). "We tested the prognostic impact of CLDN18 on the series of 45 stage IV cases, in which 10 (22.2%) tumours showed high CLDN18 expression, but the association between CLDN18 status and patients’ prognosis was not significant in this small series of advanced cancers." (PMID 31235864, 2019). "In addition, aberrant regulations of the Rho pathway, which could take place upon fusion of ARHGAP with a RhoGAP domain to CLDN18 with transmembrane domains, may influence tumor cell movements and invasiveness." (PMID 30034621, 2018). "The tumor demonstrated proficient mismatch repair (pMMR), PD-L1 combined positive score (CPS) 5, HER2-negative status, and claudin 18 (CLDN18) positivity." (PMID 42220735, 2026). "Eleven potential tumor targets were identified, including CEACAM5, TMPRSS4, COL17A1, CLDN18, and AQP5." (PMID 40379788, 2025). "It is expected to be a treatment for CLDN18.2-positive solid tumors and provide insights for the development of more universal CAR-γδ T-cell strategies for tumor immunotherapy." (PMID 40149332, 2025).
tumor (continued). "It has been shown to have direct MMAE-mediated cytotoxic effects on CLDN18.2-overexpressing tumor cells, as well as ADCC and CDC action and bystander-killing effects on surrounding tumor cells in preclinical studies." (PMID 41374966, 2025). "CLDN18.2 prevalence in GAC and gastroesophageal (GEAC) cancers ranges from 24–44% positivity, defined as ≥75% of tumor cells staining moderate-to-strong via IHC testing." (PMID 40136475, 2025). "EGFR/ERK signaling has been shown to drive CLDN18 transcription, while increased CLDN18 expression can, in turn, activate ERK1/2, forming a feedforward loop that enhances tumor cell proliferation and invasion, particularly in CCA." (PMID 41019366, 2025). "The CLDN18.2-PDL1 BsAb, Q-1802, activates a dual immune response by blocking PD-1 signaling and mediating ADCC, thereby exhibiting high anti-tumor activity in preclinical models." (PMID 41019366, 2025). "CLDN18.2 positivity of IHC 2+ in ≥20% of tumor cells was present in 97% of patients with CORR, which led researchers to make this cutoff the definition of CLDN18.2-high tumors." (PMID 40136475, 2025). "Among these agents, LM302, a novel CLDN18.2-targeted ADC, delivers a cytotoxic payload to tumor cells via monoclonal antibody-mediated targeting." (PMID 40900784, 2025). "However, despite a report suggesting upregulated CLDN18 (encompassing both isoforms) in ICC, the specific biological significance of CLDN18.2, including its associations with clinicopathological features, prognosis, and the tumor immune microenvironment (TIME), remains uncharacterized in ICC." (PMID 40951359, 2025). "Collectively, both the in vitro and in vivo results demonstrate that the immunogenic P1 peptide derived from CLDN18 (exon 5)-ARHGAP26 (exon 12) fusion can generate NRT cells with specific and promising cytotoxicity against target tumor cells." (PMID 39164472, 2024). "Our study identified the CLDN18-ARHGAP fusion gene as a critical source of immunogenic neoepitopes, a key regulator of the tumor immune microenvironment, and immunotherapeutic applications specific to this oncogenic fusion." (PMID 39164472, 2024). "We are the first to identify immunogenic neoantigens derived from the CLDN18-ARHGAP gene fusion and verify the anti-tumor ability of NRT cells." (PMID 39164472, 2024). "Here we report that CLDN18-ARHGAP fusions occur in 9% of Chinese GC patients and can generate immunogenic neoantigen peptides to induce NRT cells with robust and specific anti-tumor cytotoxicity." (PMID 39164472, 2024). "Interestingly, this report demonstrated an accurate correlation of CLDN18.2 positivity from samples collected through biopsy (38.6%) and those collected through tumor resection (37.6%), as well as samples collected from metastatic sites (39.4%) and samples collected from primary tumor sites (38.0%)." (PMID 38339430, 2024). "In this study, we developed a CLDN18.2-specific CAR-T and applied it to unilateral and bilateral mouse tumor models." (PMID 39578426, 2024). "We next dissected tumor tissues by IHC staining for the expression of CD3, CD31, and CLDN18 biomarkers, indicative of intratumoral T-cell infiltration, angiogenesis, and antigen expression, respectively." (PMID 37564658, 2023). "This suggests that in human PCa cells, Claudin-18 is mainly regulated at the transcriptional level through specific PKC signaling pathways and modified by DNA methylation, involved in tumor differentiation and migration." (PMID 36959784, 2023). "Those in the sequential group (FAP + CLDN18.2) received the prior FAP-mBBZ CAR-T cells on day 10, and CLDN18.2-mBBZ CAR-T cells were subsequently infused on day 18 after tumor cell inoculation." (PMID 37046312, 2023).